LINC01686 (long independently transcribed non-coding RNA 1686)
Gene: Long non-coding RNA gene on chromosome 1 (182,615,254 to 182,616,629, forward strand). Ensembl gene ENSG00000261504.
Diseases named in the same sentence as LINC01686 in open-access papers:
LINC01686 is named in the same sentence as 1 disease in open-access papers, as found by Europe PMC text mining. Sharing a sentence is not in itself a finding about the gene and the disease. The quoted sentences say what the papers report.
monocytic leukemia (1 paper, 2024). "This study aims to investigate the function of LINC01686 in lipopolysaccharide (LPS)‐induced inflammatory responses in the human monocytic leukemia cell line THP‐1 and its potential regulatory mechanisms involving miR‐18a‐5p and the anti‐inflammatory protein A20." (PMID 38578001, 2024).